RNF214 (ring finger protein 214)
Synonyms: DKFZp547C195
Tractability: PROTAC: ubiquitination databases record sites on it; its protein half-life has been measured.
Gene: Protein-coding gene on chromosome 11 (117,232,154 to 117,287,429, forward strand). Ensembl gene ENSG00000167257.
Subcellular location (Human Protein Atlas): Cytosol; Golgi apparatus
Gene Ontology:
Molecular function: ubiquitin-protein transferase activity
Genetic constraint (gnomAD): Loss-of-function variants: 16 observed, 55.44 expected, observed/expected ratio (o/e) 0.29, 90% interval 0.19 to 0.44. The upper end of that interval is the gene's LOEUF score, 0.44, which puts it in group 1 of 6, group 1 being the genes least tolerant of losing a copy. Missense variants: 621 observed, 777.53 expected, observed/expected ratio (o/e) 0.8, 90% interval 0.75 to 0.85. Synonymous variants: 280 observed, 287.99 expected, observed/expected ratio (o/e) 0.97, 90% interval 0.88 to 1.07.
Homologues: Orthologues: chimpanzee RNF214 (99% identical), macaque RNF214 (98% identical), dog RNF214 (95% identical), rabbit RNF214 (94% identical), pig RNF214 (94% identical), rat Rnf214 (93% identical), guinea pig RNF214 (91% identical), mouse Rnf214 (74% identical), tropical clawed frog rnf214 (32% identical), zebrafish rnf214 (21% identical), zebrafish si:ch211-139a5.1 (10% identical).
Diseases named in the same sentence as RNF214 in open-access papers:
RNF214 is named in the same sentence as 14 diseases in open-access papers, as found by Europe PMC text mining. Sharing a sentence is not in itself a finding about the gene and the disease. The quoted sentences say what the papers report.
hepatocellular carcinoma (3 papers, 2024 to 2026). A malignant tumor that arises from hepatocytes. "Notably, we identify a predicted pairing between UBE2C and RNF214, two proteins recently implicated in hepatocellular carcinoma separately but through interrelated pathways, suggesting a potential functional link mediated by RNF214-dependent ubiquitination in partnership with UBE2C." (PMID 41726935, 2026). "Furthermore, RNF214 is overexpressed in hepatocellular carcinoma (HCC) and inversely correlates with differentiation status and patient survival." (PMID 38862474, 2024). "Hepatocellular carcinoma (HCC) is one of the most common malignant tumors, and the expression and function of an uncharacterized protein RNF214 in HCC are still unknown." (PMID 38969650, 2024).
arbovirus infection (1 paper, 2025). A viral infection that is transmitted by an arthropod. "Overexpression of RNF214 suppressed, while its depletion enhanced, arbovirus infection in bat and human cells, indicating RNF214 as a potent antiviral factor." (PMID 40261845, 2025). "We show that depletion of RNF214 levels in bat or human cells sensitizes these cells to arbovirus infection, revealing a new role for RNF214 proteins in antiviral defense." (PMID 40261845, 2025). "Functional studies demonstrate that RNF214 overexpression suppresses arbovirus infection in a manner dependent on its putative E3 ubiquitin ligase activity, whereas RNF214 depletion enhances viral replication in both human and bat cells." (PMID 40261845, 2025).
Ehlers-Danlos syndrome (1 paper, 2022). The Ehlers–Danlos syndromes (EDS) are a clinically and genetically heterogeneous group of heritable connective tissue disorders (HCTDs) characterized by joint hypermobility, skin hyperextensibility, and tissue fragility. "RNF214 is a protein-coding gene linked to disorders including Ehlers-Danlos syndrome, a group of heritable tissue disorders.The PCSK7 gene encodes enzymes that process protein and peptide precursors trafficking." (PMID 36137169, 2022).
metastatic tumors (1 paper, 2024). "According to the results, Venus-RNF214 increased the quantity of lung metastatic tumors produced by both SK-HEP-1 RNF214-sg2 and MHCC97H RNF214-sg2 cells more than Venus-∆CC." (PMID 38969650, 2024). "The results revealed that the absence of RNF214 reduced the amount of lung metastatic tumors generated by SK-HEP-1 and MHCC97H cells." (PMID 38969650, 2024).
tumor (2 papers, 2024). "The data presented that high expression of RNF214, tumor recurrence, and abnormal AFP levels were independent risk factors for HCC prognosis." (PMID 38969650, 2024). "Consistently, RNF214 promotes tumor cell proliferation, migration, and invasion, and HCC tumorigenesis in mice." (PMID 38862474, 2024).
cancer (1 paper, 2024). A tumor composed of atypical neoplastic, often pleomorphic cells that invade other tissues. "By integrating bioinformatics analysis with extensive cancer databases, a growing number of proteins, including RNF214, are gradually coming into focus." (PMID 38969650, 2024).
infection (1 paper, 2025). The state of being infected such as from the introduction of a foreign agent such as serum, vaccine, antigenic substance or organism. "Furthermore, knockout of RNF214 did not alter the upregulation of interferon (IFN)-stimulated gene expression during infection or upon treatment of cells with IFN." (PMID 40261845, 2025).
neurodegenerative disease (1 paper, 2020). A disorder of the central nervous system characterized by gradual and progressive loss of neural tissue and neurologic function. "Of the shared proteins, phosphoserine aminotransferase 1 (PSAT1) and TNC (tenascin-C) were shared between AD and FXTAS, ring finger protein 214 (RNF214) was shared between PD and FXTAS, and only PSAT1 was shared between all three neurodegenerative diseases." (PMID 33585555, 2020).
RNF214 also shares sentences with these, for which no sentence is quoted: angiosarcoma (1 paper); cardiovascular disease (1); diabetes (1); glioma (1); Insulin resistance (1); migraines (1).